SIRT5 (sirtuin 5)
Diseases named in the same sentence as SIRT5 in open-access papers (continued):
Sharing a sentence is not in itself a finding about the gene and the disease.
Myocardial fibrosis (6 papers, 2021 to 2025). "Quercetin was also found to promote desuccinylation of isocitrate dehydrogenase (IDH2) via SIRT5, maintain mitochondrial homeostasis, and alleviate myocardial fibrosis, ultimately reducing the risk of HF." (PMID 41178953, 2025). "Quercetin protects mouse cardiomyocytes against inflammation, ameliorates myocardial fibrosis, and reduces the incidence of HF by activating SIRT5, which promotes IDH2 desuccinylation and maintains mitochondrial homeostasis." (PMID 41260100, 2025). "The liver SIRT5 OE mice showed a significantly smaller area of myocardial infarction and myocardial fibrosis than the WT mice." (PMID 34368135, 2021). "The results showed a significantly smaller area of myocardial infarction and myocardial fibrosis in liver SIRT5 OE mice than in WT mice, suggesting a novel cardioprotective mechanism of SIRT5 through a liver-cardiac crosstalk mechanism." (PMID 34368135, 2021). "The areas of myocardial infarction, myocardial fibrosis, and cardiac function in a model of experimental myocardial infarction were compared between liver SIRT5 OE mice and wild-type (WT) mice." (PMID 34368135, 2021). "Results revealed that, compared to WT controls, liver-specific SIRT5-overexpressing mice exhibited markedly reduced MI area and degree of myocardial fibrosis, accompanied by significantly elevated levels of secreted fibroblast growth factor 21 (FGF21) in the circulation." (PMID 41260100, 2025). "Interestingly, the liver SIRT5 OE mice showed significantly smaller areas of myocardial infarction and myocardial fibrosis than the wild-type (WT) mice." (PMID 34368135, 2021).
renal cell carcinoma (6 papers, 2021 to 2024). "In renal cell carcinoma, SIRT5 inhibits tumor progression through Warburg efect." (PMID 36568393, 2022). "Dysregulation of Sirt5/IDH2 partially contributes to Sun resistance by disturbing mitochondrial functions and affecting antioxidant capacity of renal cell carcinoma cells." (PMID 33455080, 2021).
acute myeloid leukemia (5 papers, 2023 to 2025). Acute myeloid leukemia (AML) is a group of neoplasms arising from precursor cells committed to the myeloid cell-line differentiation. "Meanwhile, SIRT5, acting as an oncogene, promotes the onset and progression of acute myeloid leukemia (AML)." (PMID 38773972, 2024). "Succinyl-thiocarbamoyl peptides like Compound 49 and NRD167, the recommended Sirt5 inhibitors, exhibit nanomolar potency and efficacy in Sirt5-dependent acute myeloid leukemia cell lines." (PMID 38474697, 2024). "SIRT5 also fosters the development of acute myeloid leukemia (AML)." (PMID 36980194, 2023). "This is exemplified in acute myeloid leukemia (AML), where SIRT5 was identified as a critical metabolic effector." (PMID 41107644, 2025). "Acute myeloid leukemia (AML) is a blood system malignancy where sirtuin 5 (SIRT5) is abnormally expressed in AML cell lines." (PMID 38585637, 2024).
clear cell renal cell carcinoma (5 papers, 2021 to 2025). "The aim of this study was to investigate the biological functions and underlying mechanisms of SIRT5 in clear cell renal cell carcinoma (ccRCC)." (PMID 34930316, 2021). "Downregulation of SIRT5 in clear cell renal cell carcinoma leads to hyper-succinylation of PDH, reducing PDH activity, which accelerates the Warburg effect and induces tumorigenesis and progression." (PMID 39781339, 2025). "SIRT5 expression data in The Cancer Genome Atlas Kidney Clear Cell Carcinoma (TCGA-KIRC) were selected, and the correlations between SIRT5 expression and various clinicopathological parameters were analysed." (PMID 34930316, 2021). "SIRT5-mediated desuccinylation of SDHA promotes renal clear cell carcinoma tumorigenesis." (PMID 36232604, 2022). "SIRT5-mediated SDHA desuccinylation promotes clear cell renal cell carcinoma tumorigenesis." (PMID 34194607, 2021). "However, a comprehensive analysis of the role of SIRTs in clear cell renal cell carcinoma (ccRCC) is still lacking, and there are few reports on the inhibitory role of SIRT5 in ccRCC." (PMID 37096064, 2023).
Hepatic steatosis (5 papers, 2018 to 2025). Steatosis is a term used to denote lipid accumulation within hepatocytes. "Malonyl-CoA is elevated in skeletal muscle and liver from obese rats and in muscle biopsies from obese and T2D patients, and liver overexpression of SIRT5 enhances glycolysis in hepatocytes and inhibits gluconeogenesis, reducing hepatic triglycerides content of hepatic steatosis." (PMID 39979670, 2025).
hypertrophic cardiomyopathy (5 papers, 2019 to 2023). A condition in which the myocardium is hypertrophied without an obvious cause. "Indeed, SIRT5 KO mice accumulated succinylated proteins in the heart and upon aging, these SIRT5-deficient mice developed hypertrophic cardiomyopathy and impaired cardiac functions." (PMID 38213532, 2023). "Sirt5 KO mice developed hypertrophic cardiomyopathy and showed reduced cardiac function during aging." (PMID 36160705, 2022). "The pattern of change in other hallmarks of hypertrophic cardiomyopathy (e.g. Anp, Bnp mRNA) and cardiac fibrotic markers (e.g. Collagen 1a1 and Collagen 3a1 mRNA) was comparable between Sirt5 KO and WT mice at 5 weeks after TAC." (PMID 30759120, 2019). "However, we did not observe any defective hypertrophic cardiomyopathy in Sirt5 KO mice at 15 weeks of age, which was also not observed in Sirt5 KO mice at 12–21 weeks of age in Hershberger’s work." (PMID 30759120, 2019).
neuroblastoma (5 papers, 2008 to 2022). Neuroblastoma (NB) is the most common solid, extracranial childhood tumor. "In HT-22 neuroblastoma cells, SIRT5 is almost always mitochondrially-associated." (PMID 19116652, 2008). "For instance, SIRT5 was identified as a safeguard against oxidative stress-induced apoptosis in cardiomyocytes and neuroblastoma cells." (PMID 31456942, 2019). "In contrast to its generally protective action in CGNs, SIRT5 expression induces apoptosis in otherwise healthy neuroblastoma cells and also exacerbates the toxic effect of HCA." (PMID 19116652, 2008). "In addition, SIRT5 plays both antiapoptotic and antioxidative roles in neuroblastoma, and the overexpression of SIRT5 significantly protects neuroblastoma cells from staurosporine-induced apoptosis." (PMID 31817470, 2019). "It has been suggested that subcellular localization of SIRT5 may determine the roles of SIRT5 in cell survival; SIRT5 produces proapoptotic effect when it was localized to the mitochondria of neurons and HT-22 neuroblastoma cells." (PMID 24386592, 2013). "We next examined whether the effects observed with SIRT1, SIRT2, SIRT3, SIRT5, and SIRT6 on the regulation of LK-induced neuronal death extended to mouse HT-22 cells, a hippocampally-derived neuroblastoma cell line." (PMID 19116652, 2008).
non-small cell lung carcinoma (5 papers, 2016 to 2025). A group of at least three distinct histological types of lung cancer, including non-small cell squamous cell carcinoma, adenocarcinoma, and large cell carcinoma. "Additionally, glutathione disulfide reductase (GSR), an enzyme that reduces GSSG into GSH, was indicated to be hypo-expressed in SIRT5-deficient non-small cell lung cancer (NSCLC) cells, thus resulting in decreased detoxification activity and ROS level augmentation." (PMID 36980194, 2023). "Among them, the expression of sirtuin (silent mating type information regulation 2 homolog 5, SIRT5) was previously associated with the resistance against the in vitro and in vivo treatments with cis-diamminedichloroplatinum, 5-fluorouracil, or bleomycin in non-small cell lung cancer." (PMID 27990096, 2016). "That is, SIRT5 overexpression limits circLRWD1 silencing-mediated reduction of DDP resistance in DDP-resistant non-small cell lung cancer (NSCLC) cells." (PMID 39479446, 2024). "Besides, quercetin can also inhibit non-small cell lung cancer via SIRT5." (PMID 39979670, 2025).
osteoporosis (5 papers, 2021 to 2026). A condition of reduced bone mass, with decreased cortical thickness and a decrease in the number and size of the trabeculae of cancellous bone (but normal chemical composition), resulting in increased fracture incidence. "Equally ambiguous remains the functional role of Sirtuin 5 (SIRT5), a mitochondrial deacylase with well-characterized involvement in aging and bone formation, in estrogen deficiency-associated osteoporosis." (PMID 42290657, 2026). "Crucially, Slc25a4-K147 succinylation drives osteoporosis progression, while Sirt5-mediated desuccinylation at this site confers protection." (PMID 41243032, 2025). "Our work reveals the Sirt5-Slc25a4-K147 axis as a novel regulatory mechanism coupling mitochondrial metabolism to bone homeostasis, offering a therapeutic target for osteoporosis intervention." (PMID 41243032, 2025). "In this study, we identified Sirt5 as a critical regulator of osteogenic differentiation in osteoporosis through comprehensive data mining of osteogenesis- and osteoporosis-related expression profiles." (PMID 41243032, 2025). "In summary, our study reveals that Sirt5-mediated desuccinylation of Slc25a4 at K147 constitutes a critical regulatory mechanism in osteoporosis pathogenesis." (PMID 41243032, 2025). "To elucidate the role of Sirt5 in osteoporosis pathogenesis, we employed an ovariectomized Sirt5 knockout mouse model to accelerate bone loss and establish osteoporosis." (PMID 41243032, 2025). "Notably, our results demonstrate the pivotal role of Sirt5-mediated mitochondrial regulation, underscoring its therapeutic potential for osteoporosis treatment." (PMID 41243032, 2025). "To determine whether Sirt5-mediated protection against osteoporosis specifically requires Slc25a4 desuccinylation, we performed genetic complementation experiments in Sirt5-deficient and wild-type backgrounds." (PMID 41243032, 2025). "Our findings demonstrate that Sirt5 exerts protective effects against osteoporosis development." (PMID 41243032, 2025). "Genetic ablation of Sirt5 confirmed its protective role against osteoporosis." (PMID 41243032, 2025). "The Sirt5 activator resveratrol has been shown to have therapeutic potential in osteoporosis." (PMID 38274381, 2024). "Based on our findings, we propose that targeting Sirt5 to block Cdc42 activity may be an option for the treatment of osteoporosis." (PMID 38274381, 2024). "Methodologically, we overexpressed Slc25a4WT and Slc25a4K147E in bone marrow in Sirt5-/- and Sirt5+/+ mice, followed by OVX to induce osteoporosis." (PMID 41243032, 2025). "Given SIRT5’s mitochondrial regulatory role, we confirmed its significant downregulation in ovariectomized (OVX) mouse bone tissue versus Sham controls, establishing SIRT5 as a master regulator of osteoporosis pathogenesis through pyruvate metabolism modulation." (PMID 41243032, 2025).
triple-negative breast carcinoma (5 papers, 2019 to 2025). An invasive breast carcinoma which is negative for expression of estrogen receptor (ER), progesterone receptor (PR), and human epidermal growth factor receptor 2 (HER2). "However, a positive association between SIRT5 expression and complete response to neoadjuvant chemotherapy in triple-negative breast cancer patients was previously shown by analyzing data from the Gene Expression Omnibus (GEO) DataSet." (PMID 31456942, 2019). "We have shown that in triple-negative breast cancer cells, SIRT5 inhibition or silencing decreased the association between GLS1 and SIRT5 while increasing glutamine metabolism, ammonia production and ammonia-induced autophagy." (PMID 37627630, 2023). "In contrast, an analysis of data from the GEO DataSet revealed high levels of SIRT5 in triple-negative breast cancer patients who showed complete response to neoadjuvant chemotherapy." (PMID 31456942, 2019). "Methods: wt and GLS1-silenced triple negative breast cancer spheroids were treated with 3-TYP, a selective SIRT3 inhibitor, and with MC3138, a new selective SIRT5 activator, both alone and in combination." (PMID 41599625, 2025). "qPCR analysis revealed that like the case in triple negative breast cancer, glutamine withdrawal resulted in increases in ATF4 and Sirt5 mRNA expression, and that Sirt5 mRNA transcript levels in cells deprived of glutamine were diminished upon the knockdown of ATF4." (PMID 35963851, 2022).
viral infection (5 papers, 2021 to 2025). "Sirt5-/- mice are more susceptible to viral infection accompanied with more viral load compared to control mice." (PMID 34158847, 2021). "Sirt5 deficiency leads to attenuated antiviral innate immunity in vivo and in vitro upon viral infection by decreasing TBK1-IRF3 activation and type I IFN production." (PMID 34158847, 2021). "Sirt5 deficient mice or macrophages were subjected to viral infection to assess in vivo and in vitro function of Sirt5 by detecting cytokines, viral replicates and survival rate." (PMID 34158847, 2021). "The role of SIRT5 and other sirtuins during viral infection is understudied and likely depends on the pathogen." (PMID 36095012, 2022). "SIRT3, SIRT4, and SIRT5 are mitochondrial deacetylases regulating a wide range of metabolic pathways that are known to be altered during viral infection as confirmed in our study." (PMID 34149631, 2021). "Sirt5 deficiency significantly decreases the production of IFN-β and inflammatory cytokines in vivo and in vitro following viral infection." (PMID 34158847, 2021). "Our work suggests that SIRT5, and potentially other sirtuins, could act as a bridge between cellular metabolism and the innate immune responses against viral infections." (PMID 36095012, 2022). "Our manuscript highlights that SIRT5 is a potential pharmaceutical target that could help against viral infections as well, and SARS-CoV-2 in particular." (PMID 36095012, 2022). "However, the biological role of Sirt5 and acylation, in pathological states such as during viral infection, remains elusive." (PMID 34158847, 2021). "However, there is uncertainty regarding whether SIRT5 contributes to the regulation of pexophagy, particularly in the context of viral infections." (PMID 40344161, 2025). "Specifically, SIRT1, SIRT2 and SIRT5 have been shown to exhibit potent pro-viral activity by facilitating the replication of a range of viral pathogens, while in certain viral infections, SIRT1, SIRT5, and SIRT6 display anti-viral properties." (PMID 40006932, 2025). "The interaction between endogenously expressed Sirt5 and DDX3 was also detected in BMDMs following viral infection." (PMID 34158847, 2021). "We thus investigated whether innate immunity pathways were up-regulated in SIRT5-KO cells, even without viral infection." (PMID 36095012, 2022).
acute kidney injury (4 papers, 2019 to 2026). Sudden and sustained deterioration of the kidney function characterized by decreased glomerular filtration rate, increased serum creatinine or oliguria. "An increase in peroxisomal fatty acid oxidation, both before and after injury, appears to underlie the protective effect of Sirt5 knockout, since specific inhibition of peroxisomal β-oxidation renders SIRT5-depleted proximal tubule cells as susceptible to in vitro acute kidney injury as controls." (PMID 38244103, 2024). "In conclusion, using HK-2 cells, we showed that Sirt5 attenuated cisplatin-induced acute kidney injury by activating Nrf2 and Bcl-2." (PMID 31815138, 2019). "In keeping with this protective hypothesis, knockout mice globally lacking Sirt5, encoding a dually targeted mitochondrial/peroxisomal deacetylase, display an increased peroxisome abundance in the proximal tubules and are less sensitive to acute kidney injury." (PMID 38244103, 2024). "Using an HK-2 cell model of cisplatin-induced nephropathy, we investigated whether Sirt5 could attenuate cisplatin-induced acute kidney injury (AKI)." (PMID 31815138, 2019).
acute myocardial infarction (4 papers, 2021 to 2025). Necrosis of the myocardium, as a result of interruption of the blood supply to the area. "In this study, we found that among sirtuin family members, Sirt4 and Sirt5 expression increased with age and decreased post‐myocardial infarction (MI) in neonatal mice." (PMID 40842073, 2025). "In a mouse model of acute myocardial infarction, SIRT5 expression was significantly upregulated in the liver." (PMID 41260100, 2025). "The results showed a significantly lower (p = 0.027) percentage of myocardial infarction in liver SIRT5 OE mice (22.84 ± 7.80%) than in WT mice (30.33 ± 7.20%)." (PMID 34368135, 2021). "We recently reported decreased serum protein succinylation and glutarylation in patients and rats with AMI, but the levels of cardiac SIRT5 were comparable before and after myocardial infarction." (PMID 34368135, 2021). "Third, the percentage of fibrosis area between liver SIRT5 OE and WT mice 5 days after experimental myocardial infarction was compared using Masson staining." (PMID 34368135, 2021). "Second, the percentage of infarction area between the liver SIRT5 OE and WT mice 5 days after experimental myocardial infarction was compared using TTC staining." (PMID 34368135, 2021). "To understand the effect of hepatic overexpression of SIRT5 on myocardial infarction, we first compared the cardiac function by using echocardiography between liver SIRT5 OE and WT mice 4 days after experimental myocardial infarction." (PMID 34368135, 2021). "Results showed elevated hepatic SIRT5 after myocardial infarction." (PMID 34368135, 2021). "As the protein levels of cardiac SIRT5 were comparable before and after myocardial infarction, other mechanisms may be responsible for the removal of serum protein acylation during AMI." (PMID 34368135, 2021). "By profiling the expression of SIRT5 before and after myocardial infarction in mice, we found AMI resulted in elevated hepatic SIRT5 protein levels." (PMID 34368135, 2021).